IL33 (interleukin 33)
Diseases named in the same sentence as IL33 in open-access papers (continued):
Sharing a sentence is not in itself a finding about the gene and the disease.
tumor (continued). "Wefound that the mRNA or protein levels of interleukin 33, soluble ST2, and membrane ST2were elevated in the serum of tumor-bearing mice when compared to WT mice." (PMID 29950152, 2018). "Results showed that decreased tumor size intumor-bearing mice was observed after neutralization of ST2L, which confirmed thesignificant role of IL-33/ST2L signaling in tumor growth." (PMID 29950152, 2018). "The data showed that MVD in the tumor stroma was significantly higher in patients with elevated IL-33 expression, suggesting that the IL-33/ST2 axis can promote malignancy and tumor aggressiveness by remodeling the TME." (PMID 30205617, 2018). "IL-33 can induce the enhanced recruitment of suppressive immune cells such as CD11b+ GR1+ and CD11b+ F4/80+ myeloid cells and Tregs into the tumor site, where these cells have a strong impact on immune microenvironment remodeling." (PMID 30547011, 2018). "In an orthotopic model of CRC liver metastasis, overexpression of IL-33 in mouse CT26 and MC-38 CRC cells enhanced tumor take, tumor growth and liver metastasis when injected into the cecum of syngeneic host mice." (PMID 30205617, 2018). "Recently, it was shown in the mouse monocyte/macrophage line RAW264.7 that IL-33 directly induces MMP-9 expression, which facilitates tumor progression, invasion, and angiogenesis." (PMID 30483263, 2018). "Tumor tissue specimens from patients suffering from NSCLC were analyzed for expression of IL-33 protein by immunohistochemistry and expression of IL-33 and ST2 mRNA by RT-quantitative PCR (RT-QPCR)." (PMID 29499051, 2018). "Depletion of FAK, IL-33, or sST2 from SCC cells prior to implantation into syngeneic host mice induced tumor regression, unless CD8+ T cells were also depleted." (PMID 30205617, 2018). "In view of the importance of IL-33 in contributing to the pathogenesis of CRC, herein, we review the critical role of IL-33 in the pathogenesis of CRC development and evaluate its potential as biomarker for assessing tumor aggressiveness and disease prognosis." (PMID 30547011, 2018). "We also found that T cell chemoattractants are significantly lower in A9 metastatic tumour cells, when compared to metastatic A9+IL-33 and primary TC1 tumour cells." (PMID 29440650, 2018). "A similar observation was recently reported in the CT26 adenocarcinoma model, where rIL-33 administration to tumor-bearing mice promoted, while IL-33 blockade reduced, the expansion of ST2+ Treg cells in tumor tissue and spleen." (PMID 30483263, 2018). "Mechanistically, it has been shown that IL-33 enhances RCC cell growth in vivo and prevents chemotherapy-induced tumor apoptosis in vitro via JNK signaling activation in tumor cells." (PMID 30483263, 2018). "In summary, our data supports a new paradigm for cancer immunology where the IL-33/ILC2 axis acts as an effector pathway that assists and mediates anti-cancer immune responses and reduces tumour metastasis." (PMID 29440650, 2018). "The overall effect is tumor immunosuppression through increased stimulation of immunosuppressive regulatory T cells by CCL5 and sequestration of IL-33 by sST2 to block its stimulation of cytotoxic T-cells." (PMID 30205617, 2018). "The impact of IL-33 on the TME was assessed by measuring mast cell density (MCD) and microvessel density (MVD) in the tumor stroma." (PMID 30205617, 2018). "IL-33 induced CRC carcinogenesis and liver metastasis by remodeling tumor microenvironment and activating angiogenesis." (PMID 30119635, 2018). "IL-33 neutralization significantly inhibited the expressions of M2 TAM-related genes including arginase 1, IL-10 and VEGF in tumor tissues." (PMID 28978138, 2017). "Tumoral expression of IL-33 was also reported to inhibit tumor growth and modifies the tumor microenvironment through CD8 T cells, favoring tumor eradication." (PMID 28978138, 2017).
tumor (continued). "IL-33 neutralization results in reduced proliferative survival of NSCLC cells, insufficient M2-polirzaied TAMs and diminished Treg cells in tumor tissues." (PMID 28978138, 2017). "A number of studies have demonstrated that IL-33 can promote CD8+ T cell function and inhibit cell growth metastasis of tumor cells." (PMID 28402273, 2017). "While tumor growth of untreated NSCLC xenografts was stable in vivo, it was significantly enhanced by IL-33 treatment." (PMID 28978138, 2017). "Systemic over-expression of IL-33 in transgenic mice promotes NK and CD8+ T cell function and inhibits tumor growth and metastasis." (PMID 28710436, 2017). "Epithelial expression of mature IL-33 correlated positively with tumor growth, and deletion of ST2 decreased tumor incidence." (PMID 28710436, 2017). "In addition, the changes in the immune parameters induced by IL-33 expression (increase in ST2+ Tregs, induction of Th2 cytokines and M2 macrophages) could also contribute to regulation of the commensal bacteria that modulate the susceptibility to tumor." (PMID 28710436, 2017). "We observed significantly higher expressions of IL-33, arginase 1, IL-10 and FoxP3 in NSCLC tumor tissues than adjacent tissues." (PMID 28978138, 2017). "IL-33 blockade restricts NSCLC outgrowth, abrogates polarization of M2 TAMs and reduces accumulations of Treg cells in tumor tissues, representing an effective and promising strategy for NSCLC treatment." (PMID 28978138, 2017). "IL-33 functions as an intrinsic molecular mechanism supporting NSCLC outgrowth and a tumor-derived factor involved in cancer immunoediting." (PMID 28978138, 2017). "However, the role of IL-33 in tumour inflammation and metastasis is unknown." (PMID 27150562, 2016). "Second, the expression of IL-33 and MHC-I by the tumours appears to be directly correlated and possibly co-regulated." (PMID 27619158, 2016). "In addition, ‘alarmin' IL-33 may also act as an immunoadjuvant to inhibit tumour growth." (PMID 27150562, 2016). "For pharmacological blocking of IL-33 functions, we treated PDGF-BB and vector tumour-bearing mice with a soluble ST2 receptor, which have been used to effectively block IL-33 functions in other experimental settings." (PMID 27150562, 2016). "Interestingly, a substantial number of IL-33 metastatic tumour cells in distal regions of the zebrafish body including the head and truck regions were coupled with co-injected macrophages, suggesting that tumour cells hijacked IL-33 stimulated macrophages for intravasation and dissemination." (PMID 27150562, 2016). "However, the expression of IL-33 by the tumours appeared to prevent the accumulation of these immune-suppressive cells, and promoted intensive infiltration by CD68+ tumour-associated macrophages and neutrophils in IL-33-expressing A9 tumours compared to unmodified A9 tumours." (PMID 27619158, 2016). "IL-33 also stimulates the secretion of S100A8/9 (a DAMP) and VEGF from these cell populations to support tumor angiogenesis and metastasis." (PMID 28119694, 2016). "When patient groups were equalized in relation to age, tumor size, status of axillary lymph nodes and AJCC stage of tumors we found that the level of tumor necrosis correlated with lower expression of IL-33, IL-33R and VEGF." (PMID 26919112, 2016). "Metastatic carcinomas express reduced levels of IL-33 and diminished levels of antigen processing machinery (APM), compared to syngeneic primary tumours." (PMID 27619158, 2016). "Thus, attenuation of IL-33 may stimulate innate antitumor immune response, but also may promote tumor necrosis which is associated with the lack of VEGF." (PMID 26919112, 2016). "Our study reveals a tumor-suppressive role for TTP in GC, and indicates the potential application of TTP for treating IL-33-mediated tumor promotion." (PMID 27074834, 2016).
tumor (continued). "The mean volume of tumours grown from A9+IL-33 cells was ~30–45% lower than from A9 controls, although both were higher as compared to the mean volume of primary TC1 tumours over the duration of study." (PMID 27619158, 2016). "IL-1β was abundant in P29 tumours at the mRNA level, particularly in the peripheral region, in B6 mice compared with those tumours in IL-33−/− mice, and IL-4, IL-6 and TRAIL expression was quite low in both types of tumours." (PMID 26775708, 2016). "Overexpression of IL-33 in transfected A9 cells induced increased expression of MHC-I, linking IL-33 to antigen presentation and suggesting that IL-33 acts upstream of this pathway to restore MHC-I expression in tumour cells." (PMID 27619158, 2016). "Interestingly, the metastatic A9 tumour microenvironment stained intensely for suppressive T-regulatory cell marker (FoxP3+), while this was not seen in the A9+IL-33 expressing tumour environment or in the negative control that are also associated with tumour immune-resistance." (PMID 27619158, 2016). "On the other hand, IL-33 signaling is necessary to generate effective CD8+ T cell responses in viral and tumor metastatic models." (PMID 27334012, 2016). "IL-33 modulates the immune response of several cells, including ILC2, Th2, and M2 macrophages, and can be derived from tumor cells, with the ability to recruit TGF-β, a cytokine that has pro-tumor activity by suppressing the activity of cytotoxic T cells (CTLs)." (PMID 41596472, 2026). "In addition, IL-33 is a pleiotropic cytokine that can activate ILC1 cells in immune reactions, such as tumor cell development." (PMID 41596472, 2026). "With respect to single treatments, DAC/IL-33 improved the survival of tumor-bearing mice although it did not significantly impact tumor growth." (PMID 40317004, 2025). "Moreover, IL-33 stimulates TAMs to produce high levels of MMP9 through activation of NF-κB, and MMP9 allows tumor cells to intravasate into the circulation." (PMID 40453088, 2025). "This provides a plausible mechanistic link by which IL-33/ST2 inhibition could downregulate PD-L1 and sensitize tumours to PD-1/PD-L1 blockade." (PMID 41284319, 2025). "Other potentially stiffness regulated genes were IL-33, HS3ST3B1, and IL-11, which were among the most differentially expressed genes between the PDECs grown in the soft matrix compared to the original uncultured stiff tumor." (PMID 40425576, 2025). "IL‐33 can upregulate the expression of endothelial adhesion molecules (PECAM1 and CD34) and organoid adhesion molecules (KRT17), thus promoting angiogenesis (cell‐to‐cell adhesion) and tumor proliferation." (PMID 40860436, 2025). "According to our results, IL33 did not directly increase the protein expression of PD-L1 or CD274 in tumor cells." (PMID 41214328, 2025). "A clear preferential migration towards the chamber containing DAC/IL-33 treated A375M, as opposed to single drug-treated (IL-33 or DAC) or untreated tumor cells was observed after 48 h of co-culture." (PMID 40317004, 2025). "The synergistic improvement in anti-tumor activity induced by Super2 and IL-33 armoring was independent of IFN-γ or perforin-mediated cytotoxicity." (PMID 41019052, 2025). "Protein complexes of IL-33 and ST2 are mainly found outside of the tumor core." (PMID 39931535, 2025). "Ultrasound revealed that the tumors that originated from the IL‐33‐knockdown group contained less blood supply and more necrosis, and vessels were mainly distributed in the tumor margin rather than the tumor core." (PMID 40860436, 2025). "Necrotic tumor also releases pro-inflammatory molecules such as interleukin-33 or HMGB1, which may foster tumor growth." (PMID 40815430, 2025). "Collectively, these findings emphasize the dominant regulatory role of IL-8 in modulating IL-17A activity during tumor invasion and highlight the absence of a direct relationship involving IL-33 in this context." (PMID 40725273, 2025).
tumor (continued). "Only wild-type PDAC mice, but not Il33-/- mice showed tumor control and induction of TLSs upon activation of LTβ receptor, which is a typical signal for TLS neogenesis." (PMID 40414898, 2025). "Evidence shows that IL-33/ST2 activation can both promote tumor development, regulating aspects like angiogenesis, invasiveness, metastasis, and immune protection, and exhibit anti-tumor effects, aiding tumor regression." (PMID 39925809, 2025). "Combined DAC/IL-33, but not the single treatments, induced significant increase in tumor-infiltrating CD4 and CD8 T cells with respect to untreated mice." (PMID 40317004, 2025). "At the molecular level, the expression of Il4, Il17a, and Il33, but not that of Tslp, Ccl20 or Ccl27a, was dramatically lower in the skin lesions of the IL-1R antibody-treated SSKO mice than in those of their IgG-treated SSKO littermates." (PMID 39939818, 2025). "The IL-33/ST2 signaling pathway plays a dual, environment-dependent role in tumor development, modulating tumor-related immunity by remodeling the TME to either promote immunosuppressive cell recruitment or inhibit tumor growth by enriching NK and cytotoxic T cells." (PMID 39925809, 2025). "Most likely, the activated IL-33 signal in the ESCC might be an epiphenomenon that contributes to the tumor-derived esophageal inflammation and tumor angiogenesis, and immune suppression." (PMID 40520454, 2025). "Together, these data suggest that targeting the IL-33/Il1rl1 signaling pathway could be a therapeutic strategy for AML through dual inhibition of the LSCs and the inhibitory tumor microenvironment." (PMID 40659660, 2025). "Interestingly, higher expression levels of IL1RL1 (gene encoding ST2) and IL-33(DVS27) correlated with shorter overall survival in patients who received radiotherapy and chemotherapy, suggesting that IL-33 may mediate the DNA damage response (DDR) of tumor cells." (PMID 40216748, 2025). "In contrast, the few PBMC infiltrating the opposite chambers containing A375M cells either untreated, IL-33 treated or DAC treated showed no or rare CD8 T cells distant from tumor cells." (PMID 40317004, 2025). "Recent mechanistic studies show that combined blockade of PD-1 and TIGIT expands tumour-reactive CD8+ T-cell clones and restores effector function, supporting the rational design of triplet regimens (e.g. PD-1 + IL-33/ST2 + TIGIT) in biomarker-selected cohorts." (PMID 41284319, 2025). "Automated quantification reveals the proportion of negative, weak, intermediate, or strong IL-33 staining in each tumor core." (PMID 39931535, 2025). "To determine the function of IL-33 in the tumor microenvironment, we used mice lacking the ST2 receptor." (PMID 39931535, 2025). "IL-33 also prevented the formation of experimental pulmonary metastasis in an eosinophil-dependent manner without an involvement of CD8+ T cells, indicating direct anti-tumor activity." (PMID 40050933, 2025). "While research specifically examining IL-33 in the context of BLCA remains limited, its established role in other cancer types suggests it could play a pivotal role in tumor–immune system interactions." (PMID 40893939, 2025). "To explore the possible mechanisms underlying the cooperative action between DAC and IL-33, we analyzed the requirement for IL-33 signaling for DAC anti-tumor efficacy in vivo in mice lacking the IL-33 specific receptor ST2." (PMID 40317004, 2025). "Thus, both direct IL-33 injection and immunotherapy with IL-33-induced FCGR3+CD103+ cDC1s increase antitumor immunity in mouse tumor models." (PMID 38825642, 2024). "However, IL-33 also can induce M2 polarization through p38-GATA3 signaling pathway, which fosters tumor progression and resolution of inflammation." (PMID 38238529, 2024).
tumor (continued). "Recently, many reports have drawn attention from the roles of IL-33/ST2L to their effects in facilitating communication between tumor cells and immune cells within the tumor microenvironment (TME), significantly influencing the remodeling of immunosuppressive TME." (PMID 38778059, 2024). "Taken together, these findings suggest that the accumulation of IL-33-induced nILC2s subsets in tumor tissues does not effectively impede tumor growth." (PMID 38430390, 2024). "The IL-33/ST2 axis alters the Treg population, thus promoting tumor progression." (PMID 38825642, 2024). "This study demonstrated that the intraperitoneal administration of IL-33 could induce the celiac inflammatory environment, activate immunologic effector cells, and reverse the immunosuppressive TIME, which delayed tumor progression and PM of GC." (PMID 38238529, 2024). "These cells include immune cells, stromal cells, non-tumor epithelial cells, and transformed (epithelial) tumor cells, which are significant sources of IL-33 in the TME." (PMID 40236667, 2024). "Immunization with IL-33 isoform plasmids enhances antigen-specific CD8+ T-cell responses, such as strong CD62L−KLRG1+ effector–memory CD8+ T-cell responses, which contribute to the suppression of tumor growth." (PMID 38825642, 2024). "Hence, these data revealed that IL-33 combined with anti-CSF1R further enhanced the antitumor effect in both abdominal dissemination and subcutaneous tumor models, indicating the importance of eliminating macrophages." (PMID 38238529, 2024). "Notably, oncogenic KrasG12D also elevates IL‐33 expression in PDA cells, thereby recruiting and activating TH2 and lymphoid cells 2, which in turn can provoke tumor growth through the secretion of protumorigenic cytokines, such as IL‐4, IL‐5, and IL‐13." (PMID 38882486, 2024). "These IL-33-expanded Treg cells are present in both immune and non-immune tissues and exert a strong suppressor effect, creating an immunosuppressive tumor microenvironment." (PMID 40236667, 2024). "In tumor tissues, IL-1α, IL-1β, IL1R1, IL1RL1, IL1F10, IL33, CASP1, and AIM2 are highly expressed." (PMID 39461030, 2024). "The In vivo mouse experiments demonstrated that IL-33 could induce the recruitment of eosinophils, CD4+ T cells, CD8+ T cells, and macrophages to HCC, significantly reducing the number of tumor nodules." (PMID 39308686, 2024). "In contrast to their WT counterparts, mice lacking IL-33 (IL-33−/−) demonstrated significantly increased tumor size and accelerated tumor growth." (PMID 38430390, 2024). "Overall, the IL-33/ST2 signaling pathway significantly influences the TME in cancer by impacting immune effector cells and regulating the recruitment of cells that either promote or inhibit tumor growth." (PMID 40236667, 2024). "Anti-fungal treatment significantly decreased intra-tumor fungi and pancreatic ductal adenocarcinoma tumor burden, increased survival via IL-33 secretion and suppressed recruitment of type 2 innate lymphoid cells (ILC2) and Th2 cells in the tumor microenvironment." (PMID 39116092, 2024). "Notably, neutralizing antibodies against IL-33 or ST2L block NF-κB activity, suppress M2 macrophage polarization, and synergistically inhibit tumor growth when combined with cisplatin treatment in vitro/vivo." (PMID 38778059, 2024). "Importantly, anti-IL-33 monoclonal antibody therapy increase the percentage of CD4+IFNγ+ T cells and decreased CD4+ and CD8+ T cells secreting IL-4 in tumour-draining lymph nodes." (PMID 38662248, 2024). "Exogenous IL-33 restored tumor-residing dendritic cell (DC) activation and maturation via direct ST2-mediated signaling and induced antitumor T-cell responses in a syngeneic tumor model and pulmonary adenocarcinoma." (PMID 37246159, 2023).